CCDC71 (coiled-coil domain containing 71)
Synonyms: FLJ12800
Tractability: PROTAC: ubiquitination databases record sites on it; its protein half-life has been measured.
Gene: Protein-coding gene on chromosome 3 (49,161,063 to 49,166,331, reverse strand). Ensembl gene ENSG00000177352.
Subcellular location (Human Protein Atlas): Nuclear membrane
Genetic constraint (gnomAD): Loss-of-function variants: 3 observed, 6.82 expected, observed/expected ratio (o/e) 0.44, 90% interval 0.2 to 1.13. That is too few expected variants to judge how well the gene tolerates losing a copy. Missense variants: 594 observed, 634.34 expected, observed/expected ratio (o/e) 0.94, 90% interval 0.88 to 1. Synonymous variants: 257 observed, 256.63 expected, observed/expected ratio (o/e) 1, 90% interval 0.9 to 1.11.
Homologues: Orthologues: chimpanzee CCDC71 (97% identical), macaque CCDC71 (97% identical), rabbit CCDC71 (88% identical), pig CCDC71 (83% identical), guinea pig CCDC71 (76% identical), mouse Ccdc71 (70% identical), rat Ccdc71 (70% identical), tropical clawed frog ccdc71 (33% identical), zebrafish ccdc71 (21% identical). Paralogues in human: CCDC71L (14% identical).
Diseases named in the same sentence as CCDC71 in open-access papers:
CCDC71 is named in the same sentence as 10 diseases in open-access papers, as found by Europe PMC text mining. Sharing a sentence is not in itself a finding about the gene and the disease. The quoted sentences say what the papers report.
depression (2 papers, 2023 to 2024). "In previous GWAS and clinical studies, these genes have been associated with neurogenesis (WNT3), neurodevelopmental delays (QRICH1), addiction (HCG27), depression (CCDC71, CYP21A2), and other brain-related disorders." (PMID 39269986, 2024).
CCDC71 also shares sentences with these, for which no sentence is quoted: anorexia nervosa (1 paper); antiphospholipid syndrome (1); anxiety disorder (1); autism spectrum disorder (1); cancer (1); Neurodevelopmental delay (1); Obesity (1); psychiatric disorder (1); schizophrenia (1).